BEX3 (brain expressed X-linked 3)
Description:
May be a signaling adapter molecule involved in NGFR/p75NTR-mediated apoptosis induced by NGF. Plays a role in zinc-triggered neuronal death. In absence of reductive stress, acts as a pseudosubstrate for the CRL2(FEM1B) complex: associates with FEM1B via zinc, thereby preventing association between FEM1B and its substrates.
Synonyms: DXS6984E; NADE; NGFRAP1; Bex; HGR74; Hero20
Tractability: PROTAC: UniProt records ubiquitination sites on it; ubiquitination databases record sites on it.
Gene: Protein-coding gene on chromosome X (103,376,299 to 103,378,301, forward strand). Ensembl gene ENSG00000166681.
Subcellular location: Nucleus; Cytoplasm, cytosol
Subcellular location (Human Protein Atlas): Cytosol
Pathways (Reactome):
Signal Transduction: NADE modulates death signalling
Gene Ontology:
Molecular function: identical protein binding; protein binding; cysteine-type endopeptidase activator activity involved in apoptotic process; molecular function inhibitor activity; signaling receptor binding; death receptor binding; nerve growth factor receptor binding
Biological process: negative regulation of protein ubiquitination; regulation of apoptotic signaling pathway; signal transduction; apoptotic process
Cellular component: cytosol; cytoplasm; nucleus
Homologues: Orthologues: chimpanzee BEX3 (100% identical), macaque BEX3 (100% identical), pig BEX3 (96% identical), guinea pig BEX3 (93% identical), mouse Bex3 (93% identical), rat Bex3 (93% identical). Paralogues in human: BEX5 (60% identical), BEX1 (40% identical), BEX2 (40% identical).
Diseases named in the same sentence as BEX3 in open-access papers:
BEX3 is named in the same sentence as 27 diseases in open-access papers, as found by Europe PMC text mining. Sharing a sentence is not in itself a finding about the gene and the disease. The quoted sentences say what the papers report.
Alzheimer disease (2 papers, 2020 to 2024). A progressive, neurodegenerative disease characterized by loss of function and death of nerve cells in several areas of the brain leading to loss of cognitive function such as memory and language. "BEX1 and BEX3 have been recently identified among the most significantly downregulated genes in excitatory neurons of the prefrontal cortex of Alzheimer’s disease patients." (PMID 33100228, 2020). "The genes brain expressed X‐Linked 1 (BEX1), brain expressed X‐Linked 3 (BEX3), and Stathmin 1 (STMN1) had been confirmed uniquely down‐regulated in excitatory‐ and inhibitory‐neuron in brain bearing AD according to single‐cell transcriptomic analysis of Alzheimer's disease." (PMID 38923860, 2024).
breast carcinoma (2 papers, 2017 to 2025). "In breast cancers, BEX3 promoted apoptosis and inhibited mouse xenograft formation." (PMID 28083995, 2017).
Intellectual disability (2 papers, 2020 to 2022). "The KEGG disease enriched under Bex3−/− regulation were thalassemia, sickle cell anaemia, transient neonatal diabetes mellitus, postaxial polydactyl, non-syndromic X-linked mental retardation, and others." (PMID 37533672, 2022). "Thalassemia, sickle cell anaemia, transient neonatal diabetes mellitus, postaxial polydactyl, non-syndromic X-linked mental retardation, and others were identified KEGG diseases enriched under the control of Bex3−/−." (PMID 37533672, 2022). "In brief, the phenotypical features of Bex3 mutant mice makes this gene an exciting candidate for future research into human neurological disorders that impact upon repetitive behavior, sociability, and intellectual disability." (PMID 33100228, 2020). "Furthermore, patients with severe intellectual disability, craniofacial dysmorphism, and autism have been reported to carry different genomic microdeletions in Xq22 encompassing BEX/TCEAL genes, with BEX3 pinpointed as one of the main candidates to cause these neurological features." (PMID 33100228, 2020).
autism (1 paper, 2020). Persistent deficits in social interaction and communication and interaction as well as a markedly restricted repertoire of activity and interest as well as repetitive patterns of behavior. "Also, a small 252-kb duplication spanning BEX3, TCEAL4, TCEAL9, and RAB40A has been reported in a patient with autism (Decipher database, ID: 290829)." (PMID 33100228, 2020).
autism spectrum disorder (1 paper, 2020). A spectrum of developmental disorders that includes autism, and Asperger syndrome. "Here we show that mutations of murine Bex3 lead to subtle craniofacial changes and have a profound impact on repetitive and social behavioral performance, two important behavior alterations required to diagnose autism spectrum disorders (ASD)." (PMID 33100228, 2020).
esophageal squamous cell carcinoma (1 paper, 2017). Esophageal squamous cell carcinoma (ESCC) is a type of esophageal carcinoma (EC) that can affect any part of the esophagus, but is usually located in the upper or middle third. "Significant overexpression of BEX3 is observed in NPC, esophageal squamous cell carcinoma (ESCC), oral dysplasia, and oral squamous cell carcinoma (OSCC)." (PMID 28083995, 2017).
head and neck cancer (1 paper, 2017). A primary or metastatic malignant neoplasm affecting the head and neck. "Among the 5 BEX members, BEX3 was the one and only one found to be significantly upregulated in head and neck cancers." (PMID 28083995, 2017).
leukoplakia (1 paper, 2016). A white patch or plaque on a mucous membrane that cannot be characterized clinically or pathologically as any other disease. "The correlation of low BEX4 expression with poor cancer-free survival in leukoplakia patients was more significant than other BEX family members including BEX1, BEX2, NGFRAP1 (BEX3) and BEX5." (PMID 27297407, 2016).
neuroblastoma (1 paper, 2017). Neuroblastoma (NB) is the most common solid, extracranial childhood tumor. "Our results from curcumin treated N2a neuroblastoma cells indicated the induction of Bex1, Bex2 and Bex3 genes prior to activation of apoptotic pathways and continued to last for 24 hours post treatment." (PMID 28145533, 2017).
teratocarcinoma (1 paper, 2017). A germ cell tumor characterized by the presence of an embryonal carcinoma component and a teratoma component. "In F9 teratocarcinoma cells, knockdown the expression of BEX3 suppressed cell growth." (PMID 28083995, 2017).
cancer (9 papers, 2015 to 2025). A tumor composed of atypical neoplastic, often pleomorphic cells that invade other tissues. "The overexpression of BEX3 highlights the potential of EPZ004777 to inhibit cancer cell survival pathways and promote apoptosis." (PMID 40136427, 2025). "Bioinformatics analyses show that EPZ004777 treatment leads to the overexpression of the BEX3 gene enhancing apoptosis processes in cancer cells." (PMID 40136427, 2025). "The treatment with EPZ004777 induces the overexpression of the BEX3 gene in cancer cells, thereby promoting apoptosis and inhibiting survival pathways in cancer cells." (PMID 40136427, 2025). "The tumour suppressor role of BEX3 protein was discovered in a xenograft MDA-MB-231 cancer cell model in mice." (PMID 37533672, 2022). "The results indicated that BEX3 upregulation is only limited on cancers originated in head and neck." (PMID 28083995, 2017). "BEX3 overexpression was a unique event in cancer developed in the head and neck regions, especially NPC." (PMID 28083995, 2017). "The confined distribution in the human cancers indicated that BEX3 is playing a unique role in the pathogenesis of cancers in head and neck regions including NPC." (PMID 28083995, 2017). "The functional implications of BEX3 in cancers remained unresolved." (PMID 28083995, 2017). "It is suggested that the BEX3 may be involved in various types of cancers." (PMID 37533672, 2022). "Thus, we proposed that BEX3 overexpression is important for the NPC cell to enrich the stemness features and acquire cisplatin‐resistant phenotype, which thereby allows the cancer cells to withstand the stressful environment created by the genotoxic chemotherapeutic agents." (PMID 28083995, 2017).
tumor (7 papers, 2016 to 2025). "Bex3 has also been reported as a pro-apoptotic protein mediated by p75NTR13 and reduces tumor formation in mouse xenograft models of human breast cancer." (PMID 28145533, 2017). "Besides, BEX3-induced downregulation of DRG-1 stimulated PC12 cell proliferation indicates its function in tumour suppression." (PMID 37533672, 2022). "In addition, Bex3-mediated inhibition of DRG-1 induced PC12 cell proliferation suggests its tumor suppressor function." (PMID 28145533, 2017). "BEX3, in comparison, was overexpressed in the primary tumor." (PMID 27297407, 2016). "Despite their contributions to tumor progression, the expression of three genes was not shown to be differentially expressed with radiotherapy (1.049-fold in BEX2, 1.057-fold in BEX3, and 1.064-fold in BEX5) in the microarray results." (PMID 34576008, 2021).
neurological diseases (2 papers, 2016 to 2020). "Notably, BEX3 is located in the interval associated with the neurological features of patients diagnosed with early-onset neurological disease trait (EONDT), which harbor different genomic deletions encompassing BEX/TCEAL genes." (PMID 33100228, 2020). "At least one of its members, Bex3, is relevant for higher brain functions in placental mammals and may be involved in human neurological disorders." (PMID 33100228, 2020).
epithelial carcinoma (1 paper, 2017). "Marked overexpression of BEX3 was observed in the laser microdissected epithelial carcinoma cells from the NPC tissues in GSE12452 (fold change = 2.707, P = 2.18E−10)." (PMID 28083995, 2017).
BEX3 also shares sentences with these, for which no sentence is quoted: infection (2 papers); genetic disorder (1); glioblastoma (1); infantile spasms (1); nasopharyngeal carcinoma (1); neonatal diabetes mellitus (1); oral squamous cell carcinoma (1); prostate carcinoma (1); schizophrenia (1); sickle cell anaemia (1); squamous cell carcinoma (1); thalassemia (1); transient neonatal diabetes mellitus (1).